NATP (N-acetyltransferase pseudogene)
Synonyms: NATP1; formerly AACP
Gene: Unprocessed pseudogene on chromosome 8 (18,370,607 to 18,371,484, forward strand). Ensembl gene ENSG00000253937.
Diseases named in the same sentence as NATP in open-access papers:
NATP is named in the same sentence as 1 disease in open-access papers, as found by Europe PMC text mining. Sharing a sentence is not in itself a finding about the gene and the disease. The quoted sentences say what the papers report.
periodontitis (1 paper, 2022). An acute or chronic inflammatory process that affects the tissues that surround and support the teeth. "Future studies are still needed to assess NATP’s microbial killing efficiency of multi-species oral biofilms on other biomaterial substrates and the effect on inflammatory response in cell culture and the tissue repair after plasma treatment in animal periodontitis models." (PMID 36103549, 2022).